INS (insulin)
Diseases named in the same sentence as INS in open-access papers (continued):
Sharing a sentence is not in itself a finding about the gene and the disease.
diabetes (continued). "Type 2 diabetes mellitus (T2DM) is a general term for different metabolic disorders, the main consequence of which is chronic hyperglycemia and it can be caused by impaired insulin secretion or impaired insulin function or both." (PMID 37394447, 2023). "The TG, LDL‐cholesterol and HDL‐cholesterol findings remained the same after adjustment for age, sex, diabetes type, diabetes duration, and percentage of participants on insulin." (PMID 37194402, 2023). "Are children with major congenital anomalies more likely to develop diabetes requiring insulin therapy, as indicated by prescriptions for insulin, than children without congenital anomalies?" (PMID 36869270, 2023). "In type 2 diabetes (T2DM), which accounts for 90% of the total world diabetes cases, pancreatic β cells produce insulin, but the utilization of insulin by cells is compromised due to inefficient insulin receptors on cell membranes." (PMID 36903269, 2023). "The dataset includes nine attributes, eight of which are related to diabetes diagnosis (pregnancy, body mass index, insulin levels, age, blood pressure, skin thickness, glucose and diabetes spectrum function) and one label attribute." (PMID 37264332, 2023). "In conclusion, we successfully triggered a direct, transient switch of pancreatic alpha to insulin-producing cells opening a future research on promising therapeutic avenue for diabetes management." (PMID 37008919, 2023). "Diabetes mellitus is a group of metabolic disorders characterized by chronic hyperglycemia resulting from defects in insulin action, insulin secretion, or both." (PMID 37547923, 2023). "Predisposing factors of DM can be traced to environmental and genetic factors, namely, changes in physical activity and dietary habits, age, resistance to insulin, and diabetes in the family medical history." (PMID 36976158, 2023). "Metformin is the first line of treatment for patients with diabetes, which lowers blood sugar and increases insulin sensitivity by inhibiting gluconeogenesis in liver cells." (PMID 37153436, 2023). "Diabetes is a chronic condition characterized by consistently high blood glucose levels because of insufficient production of insulin by the body or the ineffectiveness of the produced insulin." (PMID 36768516, 2023). "Phase angles were compared among different diabetes therapy groups (patients with untreated diabetes, patients receiving oral antidiabetic drugs, and patients receiving insulin therapy)." (PMID 37242147, 2023). "Management of diabetes during Ramadan fast is a crucial challenge for insulin users as long hours of fasting can make them more susceptible to potential complications (severe hypoglycemia, hyperglycemia, and ketoacidosis)." (PMID 36624651, 2023). "Increased expression of lncRNA PVT1 activates the oxidative stress and β-cell apoptosis; however, its silencing enhances the insulin secretory capacity, which classify the PVT1 as a diabetes-associated lncRNA." (PMID 37670346, 2023). "The continuum of progression from NGR to diabetes can be observed through longitudinal investigations that involve frequent monitoring of glucose levels, insulin sensitivity, and insulin production." (PMID 38115080, 2023). "In particular, cognitive function gradually deteriorates in type 2 diabetes, while intranasal insulin administration improves cognitive function in diabetes patients." (PMID 36834911, 2023). "Type 2 diabetes mellitus, primarily results from insulin resistance, an impaired target cell response to the biological effects of insulin." (PMID 37710310, 2023). "Hypoglycemia occurs when blood glucose levels drop below 70 mg/dL (3.89 mmol/L) and is common among individuals with insulin-treated diabetes." (PMID 37200277, 2023). "T1D generally results in diabetic ketoacidosis presentations necessitating insulin treatment within 3 years after diabetes diagnosis." (PMID 37234800, 2023).
diabetes (continued). "Critical to the development of therapeutics for diabetes are strategies for promoting insulin release while preserving pancreatic beta-cell mass." (PMID 37460527, 2023). "As insulin resistance plays a critical role in the pathogenesis of obesity and diabetes-related vascular diseases, we also explored the effect of metformin on insulin sensitivity in mouse aortic endothelial cells." (PMID 37759984, 2023). "Diabetes is characterized by elevated blood glucose levels due to inadequate insulin production or abnormalities in cellular activity." (PMID 37779767, 2023). "The well-established functional role of PAX6 in glucose-induced insulin secretion and the co-segregation of diabetes in families with aniridia provide compelling support for the pathogenicity of this mutation for diabetes." (PMID 36202929, 2023). "In rodent models, IF was shown to prevent the development of diabetes and reduce fat accumulation, improves pancreatic islet mass, insulin signaling, and decrease cell apoptosis in DIO mice after 4 cycles alternate day fasting." (PMID 36714968, 2023). "Here we present a case of a 61-year-old African male with a known case of type 2 diabetes mellitus on insulin." (PMID 37692660, 2023). "It has been established that the PPAR-γ agonists increase plasma levels of adiponectin in diabetes, and adiponectin enhances insulin sensitivity by reducing inflammation and oxidative stress." (PMID 36800950, 2023). "BMI, gender, and history of diabetes describe the patient's general condition and possible drug (e.g. insulin)‐induced intracellular potassium shifts." (PMID 36258296, 2023). "Diabetes is a disorder of dysregulated insulin action or insulin production; the maintenance of energy balance strongly influences the development and progression of disease." (PMID 36984824, 2023). "In fact, the first description of the disorder was established in 1933, when a diagnosed in a lady living with diabetes showed intense discomfort after starting insulin treatment." (PMID 37513978, 2023). "Type 2 Diabetes Mellitus is a chronic metabolic disorder characterized by inadequate insulin production and consequentially high blood glucose." (PMID 37895163, 2023). "Improvements were found for children, adolescents, and/or their caregivers for diabetes-related distress, insulin delivery satisfaction, and system usability (all P < 0.05)." (PMID 40303234, 2023). "Our results reveal the role of FSH in regulating pancreatic islet insulin secretion and provide avenues for future clinical investigation and therapeutic strategies for postmenopausal diabetes." (PMID 37914684, 2023). "The effects of algae extract on insulin secretion and sensitivity have been the subject of extensive investigation, shedding light on their potential for glycemic control and diabetes management." (PMID 37763235, 2023). "It is estimated that nearly 29% of people with diabetes require insulin to control their blood glucose levels, and maintaining optimal glycemic control usually requires patients to perform self-monitoring of blood glucose (SMBG)." (PMID 37976255, 2023). "Zafirlukast also proved to be a potential candidate for a therapeutic intervention in diabetes, since it enhanced insulin secretion and prompted the activation of Ca2+/calmodulin-dependent protein kinase II and extracellular signal-regulated kinase signaling." (PMID 37298790, 2023). "In a recent international study evaluating the incidence of hypoglycemia in patients with insulin-treated diabetes, hypoglycemic events were reported by 97.4% of participants with T1D, with an estimated rate of 6.86 events per patient per month." (PMID 37888065, 2023). "miR-34a directly regulates SIRT1, which is a molecule that regulates insulin release in the beta pancreatic cells that are damaged in diabetes." (PMID 37927446, 2023).
diabetes (continued). "We included all subjects with diabetes conditions, including Type 1 diabetes, Type 2 diabetes, newly diagnosed diabetes, controlled or uncontrolled diabetes, those who received insulin or oral diabetes medication." (PMID 37807699, 2023). "As a result, even at modest doses, the injection of an extract comprising rutin, quercetin, kaempferol, and acetogenins appears to be beneficial in controlling diabetes metabolic abnormalities by increasing the insulin signalling pathway." (PMID 36836708, 2023). "Our data indicate a segregation of a higher cardiovascular risk for non-fatal events, with potential impact on survival, only to AF patients with insulin-requiring diabetes." (PMID 35976428, 2023). "In conclusion, this study was the first to assess the clearance and reduction rates of insulin and glucagon in patients with diabetes undergoing HD." (PMID 37445782, 2023). "It possesses a targeted destructive effect on pancreatic β cells, and it compromises insulin production to induce diabetes." (PMID 36761194, 2023). "Evaluation of the effects of algae extracts on insulin secretion and sensitivity provides valuable insights into their potential therapeutic applications in glycemic control and diabetes management." (PMID 37763235, 2023). "Studies using a model of hyperuricemia with induction by potassium oxonate demonstrated a relationship between the increase in uric acid and insulin resistance; therefore, hyperuricemia is a possible factor triggering diabetes." (PMID 37760978, 2023). "PCI with DES in patients with insulin-treated diabetes mellitus (ITDM) is associated with a significantly higher target lesion failure rate and higher need for revascularization compared to PCI in patients with non-insulin-treated diabetes mellitus (NITDM)." (PMID 36975883, 2023). "Diabetes mellitus (DM) is characterized by metabolic dysregulation resulting from impaired insulin secretion and/or insulin resistance." (PMID 37954576, 2023). "Type 2 diabetes mellitus (T2DM), which is non-insulin dependent, is also characterized by deficient insulin; however, this type is triggered by a malfunctioned interplay between insulin blood levels and cells’ insulin insensitivity." (PMID 37371102, 2023). "This meta-analysis compares the efficacy and safety of Closed-Loop Control (CLC) to Sensor-Augmented Insulin Pump (SAP) for adolescent patients with Type 1 Diabetes Mellitus (T1DM)." (PMID 37574494, 2023). "After that, insulin needs slowly declined, and the patient stopped insulin and metformin treatment at the same time two months after the diabetes diagnosis." (PMID 37864241, 2023). "Type 2 diabetes mellitus (T2DM) is a metabolic condition characterized by hyperglycemia caused by a combination of pathophysiological variables, primarily insulin resistance and insufficient insulin production." (PMID 37107924, 2023). "Insulin secretagogues, which include sulfonylureas and meglitinides, are second-line therapies for diabetes." (PMID 36789141, 2023). "In type 1 diabetes mellitus (T1DM), C-peptide and insulin are deficient, and progressive beta-cell dysfunction can also be observed in the late stage of T2DM." (PMID 37745697, 2023). "Strategies applied have included time to diabetes, insulin use, stratification based on changes in C-peptide, and identification of individuals exhibiting less C-peptide loss compared to placebo." (PMID 37794169, 2023). "Pharmacological treatment of patients with diabetes mellitus currently focuses on stimulating insulin secretion." (PMID 36614256, 2023). "Previous studies have shown that the gut microbiome can affect insulin sensitivity and improve glucose management, which can reduce or delay the progression of pre-diabetes to type 2 diabetes mellitus." (PMID 37038214, 2023). "Diabetes mellitus (DM) is a metabolic disorder characterized by insulin resistance, where hyperglycemia is believed to trigger oxidative stress, contributing to insulin function impairment." (PMID 38107710, 2023).
diabetes (continued). "The heart weight reveals (despite similar Anp and Bnp expression levels) a blood-pressure-independent increase in weight in response to diabetes, since it is prevented by insulin treatment." (PMID 38069331, 2023). "This gene was found to be involved in glucose and lipid metabolism and in regulating insulin secretion, where it plays important roles in carbohydrate intolerance and diabetes." (PMID 37147786, 2023). "Adolescents reported behavioral changes including increased blood sugar checks, increased insulin administration and overall improved diabetes management." (PMID 37313442, 2023). "For example, in some of these studies, diabetes progression was defined as early initiation of insulin therapy, glycaemic deterioration, and pancreatic beta-cell dysfunction and participants were followed up for a longer duration." (PMID 37858088, 2023). "Diabetes mellitus, commonly known as diabetes, is a metabolic disorder characterized by high blood sugar levels (hyperglycemia) due to defects in insulin secretion, insulin action, or both." (PMID 36685073, 2023). "Affected individuals cope with progressive insulin resistance by ever-increasing insulin secretion, up to the point where this adaptive strategy becomes insufficient and type 2 diabetes mellitus (DM2) develops." (PMID 37929025, 2023). "This leads to an upsurge in the production of inflammatory cytokines that disrupt the normal functioning of pancreatic β-cells, promote insulin resistance, and consequently contribute to the onset of diabetes." (PMID 37836510, 2023). "This program commenced an intervention to provide care for all young people < 26 years of age with diabetes in Burkina Faso in 2013, donating insulin and glucose-monitoring supplies." (PMID 37777715, 2023). "Treatments that can boost insulin sensitivity and reduce endogenous insulin levels are suitable approaches to manage diabetes and its metabolic complications." (PMID 38069300, 2023). "Diabetes is a long-term medical condition that occurs when the pancreas fails to produce adequate amounts of insulin or when the body becomes insulin resistant, resulting in high blood sugar levels." (PMID 38053195, 2023). "During follow-up, 3 more patients started insulin therapy; both patients 1 and 9 started insulin therapy 5 years after diabetes diagnosis and patient 4 started insulin therapy 25 years after diagnosis." (PMID 36793123, 2023). "Inadequate insulin production, hyperglycemia, and decreased insulin utilization all contribute to DM (diabetes mellitus), which is a highly prevalent chronic metabolic condition." (PMID 37373340, 2023). "In our pDIABGRAFT cohort, biological markers of diabetes were in the normal range for HbA1C, fasting glucose and insulin levels." (PMID 36824650, 2023). "The AP continuously monitors interstitial glucose level (IGL) by using a continuous glucose monitoring (CGM) sensor and infuses insulin to manage diabetes to be within 70–180 mg/dL (called the euglycemic range), using a control algorithm." (PMID 36983097, 2023). "Diabetes-related genes in the sortitin family of vascular protein sorting-10 domain (VpS10) genes are correlated to AD in diabetics, and their malfunction can result in Aβ accumulation and insulin/glucose malfunction." (PMID 37239068, 2023). "Regular insulin injections can control the progression of diabetes and prevent the occurrence of complications." (PMID 37501783, 2023). "RAGE is linked with development of cancers in patients with obesity and diabetes, by dysregulation of insulin/IGF signalling and promotion of pertinent meta-inflammation." (PMID 37970208, 2023). "The current management of type 1 diabetes mellitus (T1DM) involves the use of intensive insulin therapy—either by insulin pump therapy or multiple daily injection (MDI) therapy—and carbohydrate counting." (PMID 40303273, 2023).
diabetes (continued). "Patients diagnosed with type 1 diabetes mellitus (T1DM) require multiple daily insulin injections, which can potentially lead to severe hypoglycemia and give rise to symptoms such as anxiety, fatigue, and loss of consciousness." (PMID 39698026, 2023). "We further conducted comprehensive subgroup analyses according to diabetes status, including diabetes duration, number of oral hypoglycemic agents, and insulin use in addition to demographic characteristics and smoking status." (PMID 36928679, 2023). "Of the patients with diabetes, four used insulin and others had comorbidities, including dyslipidaemia (92.59%), hypertension (66.67%), coronary artery disease (11.11%), cirrhosis (11.11%) and chronic kidney disease (3.7%)." (PMID 36992267, 2023). "Diabetes develops when insufficient insulin is secreted to meet the requirements of an individual’s insulin sensitivity." (PMID 37409234, 2023). "For example, the UKPDS (United Kingdom Prospective Diabetes Study) found that at least 50% of LADA patients required insulin treatment 6 years post-diagnosis." (PMID 37373160, 2023). "A considerable proportion of individuals with aDM from sub-Saharan Africa have ketosis-prone diabetes, characterized by urinary ketone bodies and reserved beta-cell function after stabilization of blood glucose through initial insulin treatment." (PMID 37402743, 2023). "Regarding diabetes-specific characteristics, 420 (26.5%) to 689 (37.4%) of all individuals were insulin users and 256 (16.1%) to 541 (29.4%) of all individuals had diabetic complications." (PMID 37204790, 2023). "Studies reporting outcomes on: prevalence/incidence of T2D and pre-diabetes, fasting blood glucose and 2-hour plasma glucose, glycated haemoglobin, insulin and Homeostatic Model Assessment for Insulin Resistance levels." (PMID 37015791, 2023). "These systems have shown considerable potential in delivering protein therapeutics for chronic and autoimmune diseases, exemplified by their successful administration of insulin for patients with conditions such as type 1 diabetes mellitus." (PMID 37504412, 2023). "In the Insulin-treated diabetic rats, diabetes was controlled by subcutaneous NPH-insulin injection daily." (PMID 37396950, 2023). "The case with undetermined cause of death (case #13) had a history of hyperadrenocorticism and diabetes, controlled with trilostane and insulin applications at home." (PMID 38030630, 2023). "Clinically, a retrospective hospital cohort study found that although metformin users did not perform better than non-users in overall survival (OS) and disease-free status, they performed better than insulin and oral diabetes medication-treated AML patients." (PMID 36830619, 2023). "The selected data contain samples from three types of patients after taking insulin treatment: patients with diabetes (DB), patients with insulin sensitivity (IS), and patients with insulin resistance (IR)." (PMID 38136941, 2023). "Harnessing the glycemic-regulating properties of algae-derived natural products has the potential to improve glycemic control, enhance insulin sensitivity, and ultimately improve the quality of life for individuals living with diabetes." (PMID 37763235, 2023). "The SEARCH for Diabetes in Youth study found that about 18% of adolescents and young adults with T1D skip their insulin doses." (PMID 36837546, 2023). "One hundred years after the discovery of insulin, advancements have been made in diabetes treatment, particularly in the development of new monitoring and glycemic correction devices." (PMID 37628498, 2023). "Diabetes mellitus is a chronic metabolic disease characterized by hyperglycemia that arises due to insufficient insulin production from the pancreas or from inadequate insulin utilization by the body, or a combination of both." (PMID 36984824, 2023).